IL5 (interleukin 5)
Diseases named in the same sentence as IL5 in open-access papers (continued):
Sharing a sentence is not in itself a finding about the gene and the disease.
eosinophilic diseases (continued). "While anti-IL-5/5R and anti-IL-4/13 monoclonal antibodies (mAbs) efficacy in systemic eosinophilic diseases is established, data on EM are lacking." (PMID 42011880, 2026). "However, IL-5 is not essential for basal eosinophil development as IL-5 blocking antibodies reduce eosinophil counts in eosinophilic diseases drastically, but not completely." (PMID 40276331, 2025).
malaria (37 papers, 2009 to 2025). Malaria is a serious and sometimes fatal disease caused by a parasite that commonly infects a certain type of mosquito which feeds on humans. "In a population of south Asian malaria patients, increased levels of IL-5 was associated with reduced severity of disease." (PMID 24433482, 2014). "Previous episodes of malaria during infancy showed weaker effects, but a high number of episodes was associated with a reduced IL-5 response to cCFP (aGMR 0.84 (0.76, 0.95)) and an increased IL-10 response to TT (aGMR 1.18 (1.03, 1.34))." (PMID 21040693, 2010). "For malaria, these effects were mainly short-term, observed only in the presence of current infection; however, decreased IL-5 cCFP and increased IL-10 TT responses were associated with both current and previous malaria." (PMID 21040693, 2010). "In this systematic review, differences of IL-5 levels between malaria and uninfected controls, and between severe and uncomplicated malaria were synthesized." (PMID 37537570, 2023). "First, there were few studies investigating IL-5 in malaria, so the results of this review were limited." (PMID 37537570, 2023). "In the literature, there is only a small number of studies investigating IL-5 levels in malaria; thus, further research is required to determine how this cytokine contributes to the disease’s pathophysiology." (PMID 37537570, 2023). "For this systematic review, 11 studies that used bead-based assays demonstrated homogeneous results of the IL-5 levels between malaria cases and uninfected controls." (PMID 37537570, 2023). "One report demonstrated higher levels of IL-5 in patients with cerebral malaria than in those with uncomplicated malaria." (PMID 37537570, 2023). "Meanwhile, in Asia similar or lower IL-5 levels were observed in severe malaria cases relative to uncomplicated malaria cases." (PMID 37537570, 2023). "The differences in IL-5 levels between malaria and uninfected controls, and between severe and uncomplicated malaria were synthesized by narrative synthesis." (PMID 37537570, 2023). "Heterogeneity of IL-5 levels between severe malaria and uncomplicated malaria was observed with respect to geographical area." (PMID 37537570, 2023). "Out of these studies, 12 studies demonstrated similar levels of IL-5 between malaria and uninfected controls." (PMID 37537570, 2023). "Regarding the methods used for IL-5 measurement, studies that used bead-based assay showed either similar or higher IL-5 levels in severe malaria than in uncomplicated malaria." (PMID 37537570, 2023). "Qualitative syntheses showed the heterogeneity of IL-5 levels between different severities of clinical malaria and uninfected controls." (PMID 37537570, 2023). "Nonetheless, other studies demonstrated higher or lower IL-5 levels in patients with severe malaria than in those with uncomplicated malaria." (PMID 37537570, 2023). "IL-2 and IL-5 levels were observed as either lower or higher in malaria coinfections compared to intestinal parasite monoinfection." (PMID 36716305, 2023). "Interleukin-5, IL-1α, and IL-10 were significantly higher in malaria seropositive than seronegative volunteers." (PMID 38274822, 2023). "Studies that used ELISA found similar or lower levels of IL-5 in severe malaria than in uncomplicated malaria." (PMID 37537570, 2023). "In Africa, IL-5 levels were either similar or higher in severe malaria cases relative to the levels in uncomplicated malaria." (PMID 37537570, 2023). "Meanwhile, heterogeneity of IL-5 levels between malaria cases and uninfected controls was observed among pregnant women and adult participants." (PMID 37537570, 2023). "Given the limited number of published studies on IL-5 levels in malaria, there is a need for additional research to determine the function of this cytokine in the pathogenesis of malaria." (PMID 37537570, 2023).
malaria (continued). "The comprehensive review suggests that IL-5 levels are unchanged in patients with different levels of clinical severity of malaria and uninfected controls." (PMID 37537570, 2023). "Searches for studies that reported IL-5 levels in patients with malaria (any severity) and/or uninfected individuals were performed in Web of Science, PubMed, EMBASE, Scopus, CENTRAL, and MEDLINE, between 1st and 10th October, 2022." (PMID 37537570, 2023). "In the malaria-exposed volunteers, numbers of IL5- and IFNγ-secreting cells increased following vaccination, unexpectedly this increase appeared to be more pronounced in the Saline group." (PMID 33854065, 2021). "In the pathogenic process of malaria, the cellular immune response is mediated by Th1 profile T cell lymphocytes with IFN-γ production and Th2 profile, with IL-4 and IL-5 cytokines, to eliminate the parasite." (PMID 30126413, 2018). "IL5 levels were also observed to be significantly high in mild malaria patients when compared to severe malaria or cerebral malaria patients who had low/intermediate levels of IL5." (PMID 30558622, 2018). "Concentrations of IL-5 in acute infection of all three types of malaria were similar to those of healthy controls, although the levels of IL-5 in acute CM (median, 1.74 pg/ml) were significantly higher (P < 0.05) than the levels in UCM (median, 1.54 pg/ml)." (PMID 28122790, 2017). "A previous study reported elevated levels of IL-5 in mild compared to severe malaria patients suggesting a protective role of this cytokine." (PMID 27168977, 2016). "The role of IL-5 in the context of malaria has so far been studied to a very limited extent and needs further investigation." (PMID 25889652, 2015). "The amelioration malaria severity is achieved by the combined induction of Th1 and Th2 immune responses with increased interleukin (IL)-5 and IFN-γ production." (PMID 26377900, 2015). "Immigrants had higher levels of IL-2, IL-5 and IL-8 compared to semi-immune adults with malaria (P≤0.0200)." (PMID 23967342, 2013). "IFN-γ, IL-5 and IL-13 to TT were reduced in HIV-exposed-uninfected infants; infant malaria and HIV were associated with lower IFN-γ, IL-5 and IL-13 responses to both immunogens." (PMID 21040693, 2010). "Current infant malaria and infant HIV infection were associated with broad reductions in IFN-γ, IL-5 and IL-13 responses." (PMID 21040693, 2010). "In an adult population in a malaria-endemic region of India, high levels of IL-12, IL-5, and IL-6 discriminated severe forms of malaria from mild malaria." (PMID 19680452, 2009). "IL-5 in malaria co-infections was demonstrated by four studies." (PMID 37537570, 2023). "Fifteen studies reported IL-5 levels in both malaria and uninfected controls." (PMID 37537570, 2023). "For the anti-inflammatory cytokines (IL-4, IL-5, IL-10, IL-13), only the concentrations of IL-1RA showed a significant difference between children with sepsis compared to children with either clinical malaria or febrile controls." (PMID 35811678, 2022). "Also, elevated levels of TGF-β, TNF-α, IL-10, and IL-1β were found in cerebral malaria, while IL-2, IFN-γ, IL-5, IL-6, and IL-12 were only increased in mild malaria." (PMID 31878288, 2019). "IL-5 levels in all three malaria types were similar in acute infection and in convalescence." (PMID 28122790, 2017). "Furthermore, HB and HT had several negative interactions with inflammatory mediators (IL-17, IL-12, IL-5, IL-4) in the malaria group." (PMID 26271921, 2015). "In summary, immigrants returning from endemic areas with malaria had higher serum concentrations for some cytokines/chemokines (IL-2, IL-5, IL-8) compared to semi-immune adults with malaria, suggesting that this profile is associated with a partial loss of immunity." (PMID 23967342, 2013).
malaria (continued). "In the present study, fine association mapping for a cytokine gene cluster including IL4, IL5, and IL13 on chromosome 5q31 was conducted using the same malaria subjects to refine the region containing a primary variant or a haplotype susceptible to severe malaria." (PMID 19840389, 2009). "The positive correlation between IFN-γ and anti-inflammatory or eosinophil-related cytokines such as IL-5 and IL-13 suggests that a balance of co-increasing pro-inflammatory and anti-inflammatory cytokines in a suitable range may benefit malaria clearance and prognosis." (PMID 41552719, 2025). "The role of cytokines such as interleukin-5 (IL-5) in the pathogenesis of malaria remains unclear." (PMID 37537570, 2023). "Indeed, in future studies it would be preferable to explore other immune responses induced by these PSNPs vaccines in the context of blood-stage malaria, including investigating other cytokines (i.e., TNF, IL-5, IL-17) in addition to the hallmark Th1 and Th2 cytokines IFN-γ and IL-4, respectively." (PMID 30930890, 2019). "Circulating concentrations of IL-4, IL-5, and IL-7 differed across the groups (P < 0.001 for all) and were significantly elevated in the G[+] and G[−] coinfected children, relative to both children with malaria-only (P < 0.001 for all) and healthy controls (P ≤ 0.024 for all), respectively." (PMID 27418744, 2016). "However, it was expected that the levels of IL-10, IFN-γ, and even IL-5 presented differences between individual experiencing different number of malaria episodes due to the fact that these cytokines are also produced by cells from the adaptive immune response." (PMID 24741587, 2014). "Children who have blood smear detectable malaria have been found to have higher levels of IL-6, compared with children who do not have blood smear detectable malaria infections and circulating IL-5 levels were elevated in children who had detectable S. mansoni eggs." (PMID 19149774, 2009). "Increased TNF, IFN-γ, IL-1, IL-2, IL-6, IL-10, TGF-β, CCL2, CCL3, and G-CSF levels and decreased IL-5, IL-12, IL-17, and CCL11 levels were observed in malaria monoinfection compared to intestinal parasite monoinfection." (PMID 36716305, 2023). "Distinct cytokine profiles in malaria and schistosomiasis coinfections were TNF, IFN-γ, IL-4, IL-5, IL-10, TGF-β, and CXCL8." (PMID 36716305, 2023). "This systematic review sought to synthesize variations in IL-5 levels between severe and uncomplicated malaria, as well as between malaria and controls not afflicted with the disease." (PMID 37537570, 2023). "The majority of the included studies (12/15 studies, 80%) found no change in IL-5 levels between malaria cases and uninfected controls." (PMID 37537570, 2023). "An analysis of the cord blood revealed that TNF, IL-1β, and IL-5 were associated with severe malaria but IL-4, IL-6, IFN-γ, and IL-10 did not relate to severe malaria." (PMID 36668942, 2023). "When stratified by malaria sero-status, IL-1α (p=0.034), IL-5 (p=0.023) and IL-10 (p=0.024) were significantly higher in malaria sero-positive than sero-negative volunteers." (PMID 38274822, 2023). "In addition, both coinfected groups had increased IL-4, IL-5, IL-7, IL-12, IL-15, IL-17, IFN-γ, and IFN-α and decreased TNF-α relative to malaria alone." (PMID 27418744, 2016). "Second, the meta-analysis to pool the mean difference in IL-5 levels among severe malaria, uncomplicated malaria, and uninfected controls could not be performed due to the few studies reporting quantitative data for IL-5 levels between groups of participants." (PMID 37537570, 2023). "In malaria-naive volunteers the Alhydrogel® group showed significant increases in the number of IL5 secreting cells following vaccinations, whereas no clear-cut IL5 responses were found in the GLA-SE group." (PMID 33854065, 2021).
malaria (continued). "However, for the malaria group, four distinct correlation patterns were observed; first pattern (CCL4, CCL2, CCL3, IL12 and IL2), second pattern (IL-17A, IL-1β, CCL11, IL4), third pattern (IL5, IL7, IL13), and fourth pattern (IL1RA, CXCL10, TNFα, IL2R, CXCL9, IL6)." (PMID 35811678, 2022). "It was found that HB and HT displayed several negative significant interactions mainly with IL-4, IL-5, IL-12p70, and IL-17, whereas ALT interacted negatively with IL-4 and IL-7 in the malaria group." (PMID 26271921, 2015). "A study in a seasonal malaria transmission area in Kenya found no seasonal differences in the frequency of IFN-γ and IL5 ELISpot responses, but higher frequencies of ELISpot responses to IL10 and TNF during the high transmission season compared to the low transmission season." (PMID 26830334, 2016). "PBMCs (1×106 cells/ml) from malaria infected (n=23) and non-infected (n=7) individuals were stimulated with mycoplasma free P. falciparum parasites (at a ratio of 1:5) and after three days IFN-γ, IL-10, and IL-5 were measured in supernatant." (PMID 23294670, 2013). "In a prospective birth cohort study in Kenya, children of malaria-infected women whose CBMC did not produce cytokines (IFN-γ, IL-2, IL-13, and/or IL-5) in response to blood stage malaria antigens were at increased risk of infection and had lower hemoglobin levels during childhood." (PMID 24130857, 2013).
Sepsis (32 papers, 2008 to 2025). Sepsis is defined as life-threatening organ dysfunction caused by a dysregulated host response to infection. "GEE results revealed that zone 1 ROP, stage 3 ROP, older baseline PMA, RDS, NEC, and sepsis were associated with increases or decreases in the serum levels of GM-CSF, IL-5, IL-15, ICAM-1, TNF-α, and TNFR-2 in premature infants." (PMID 38259597, 2023). "It has been reported that IL-5 protects mice from sepsis caused by cecal ligation by targeting monocytes, so as to avoid lung injury." (PMID 34057015, 2021). "In contrast, the Th type 2 (Th2) responses (secrete IL-4, IL-5, IL-13 and IL-10) were elevated, leading to a suppressed adaptive immune response and increased susceptibility to sepsis." (PMID 34209240, 2021). "According to our findings, it has been described that increased serum levels of IL-5 and IL-6 were associated with reduced microbial clearance and higher mortality rates in sepsis." (PMID 26975045, 2016). "Notably, the interaction between BAFF-R on IgD+ CD38br B-cells and IL-5 was found to elevate IL-5 levels, indirectly increasing sepsis susceptibility." (PMID 39076981, 2024). "A low level of IL-5 is associated with lung death and tissue damage, and thus, IL-5 treatment may reduce the mortality associated with sepsis." (PMID 34499695, 2021). "Therefore, we analyze that IL-5 can control the systemic infection caused by sepsis by restoring the specific immune function." (PMID 34057015, 2021). "As expected, our analysis revealed a significant link between the MFI of BAFF-R on IgD+ CD38br B-cells and sepsis, with interleukin-5 (IL-5) acting as a mediator." (PMID 39076981, 2024). "In conclusion, IL-5 can alleviate lung injury by regulating the immune response and inhibiting the systemic inflammatory response induced by sepsis." (PMID 34057015, 2021). "In another study, IL-33 deficiency aggravated sepsis-induced lung injury, while supplementation with IL-5 reversed this effect in IL-33 knockout mice, suggesting that IL-33 participates in the process of sepsis-induced lung injury by regulating IL-5 release." (PMID 33628366, 2021). "In vivo injection of IL-33 can stimulate Th2 cells to release IL-5 and IL-13, thus improving survival rate the pathogen control in sepsis mice." (PMID 34057015, 2021). "The aim of this study is first to investigate the effect of IL-5 on ALI in sepsis rats and provide a theoretical basis for the intervention treatment of ALI in sepsis patients." (PMID 34057015, 2021). "Clinically, anti-sepsis targeted therapeutic effects of IL-38 is amplified when combined with IL-5, IL-7, IL-30, and IL-33." (PMID 34830435, 2021). "IL-5Rα expression on lung and blood neutrophils and macrophages was recently reported in humans in a sepsis model, where IL-5 was also shown to be protective in an eosinophil independent manner." (PMID 31415658, 2019). "IL-5RA is the receptor of IL-5, which has been proposed as a viable therapy for sepsis and is required for attraction and activation of eosinophils by Th2 cells." (PMID 30463588, 2018). "Anti-inflammatory interleukins (IL-4, IL-5, IL-10) were significantly lower in sepsis patients and close to the lowest detection limit of the assays." (PMID 29379043, 2018). "Linch and his colleagues’ results demonstrated that IL-5 was protective during sepsis through improving survival and host control of infection." (PMID 26586517, 2015). "As anti-inflammatory cytokines can also play a role in the response to severe sepsis we next looked at the levels of IL-10, IL-4, IL-11 and IL-5." (PMID 21124895, 2010). "This eosinophil production was enhanced by IL-4 and IL-5, and suggests a T-helper lymphocyte type 2 cytokine activation in response to sepsis after traumatic injury." (PMID 18435836, 2008). "This similarity might contribute to the observed significant correlation between the MFI of BAFF-R on IgD+ CD38br B-cells and sepsis, as mediated by IL-5 levels." (PMID 39076981, 2024).